BCL2 (BCL2 apoptosis regulator)
Diseases named in the same sentence as BCL2 in open-access papers (continued):
Sharing a sentence is not in itself a finding about the gene and the disease.
hepatocellular carcinoma (continued). "EI-SP elevated the amount of the proapoptotic Bax protein while it reduced the amount of the antiapoptotic protein Bcl-2 in human hepatoma hepG2 cells." (PMID 36286449, 2022). "AFP can activate the PI3K/AKT signalling, stimulates the transcription cofactor mTOR, STAT3, HIF‐1α and Bcl‐2, which regulates the expression of oncogenes, as well as promotes angiogenesis and the growth of the hepatoma cells." (PMID 36181321, 2022). "It promotes apoptosis of hepatocellular carcinoma H22 through regulating the cell cycles, upregulating Map2k6 expression, and downregulating Bcl-2 gene expression in hepatoma cells." (PMID 35911149, 2022). "To clarify the regulatory mechanism of IVIG-induced apoptosis in hepatocellular carcinoma cells, we detected Bcl-2 and Bax levels in the rat livers." (PMID 35874633, 2022). "BMP4 promotes hepatocellular carcinoma proliferation through JNK1-mediated autophagic activation of Bcl-2 phosphorylation." (PMID 34221974, 2021). "The findings suggest that the EO from A. lanatum has a controlling effect on hepatoma cells (i.e., the HepG2 liver cancer cell line) through regulation of the apoptotic markers BCL-2 and CASPASE-3." (PMID 35009072, 2021). "EGCG combined with radiotherapy can further reduce the expression of the apoptosis suppressor bcl-2 and increase the expression of apoptosis-related proteins in hepatocellular carcinoma cell lines." (PMID 34178681, 2021). "A report confirmed that a natural chalcone, has been shown to exert growth inhibitory effects on the human Hepatocellular carcinoma cells serves as a transcription suppressor of anti-apoptotic genes like Bcl-2 and Bcl-xL." (PMID 33927626, 2021). "The apoptosis suppressor protein Bcl-2 and the pro-apoptotic proteins Bax, cleaved caspase-3, and caspase-3 are key in the process of apoptosis in hepatoma cells." (PMID 34048194, 2021). "Caffeine combined with 5-FU significantly increases the apoptotic level by up-regulating cleaved PARP and down-regulating Bcl-2 and Bcl-xL expressions in hepatocellular carcinoma (HCC) cells." (PMID 34684653, 2021). "COMMD10/NF‐κB axis promotes apoptosis by modulating Bcl‐2/Bax/caspase‐9/3 pathway in hepatocellular carcinoma." (PMID 34047468, 2021). "Many reports have confirmed that AFB1 can be induced by apoptosis with increased expression of bax, caspase-3 and bcl-2 during hepatocellular carcinoma formation." (PMID 32375309, 2020). "To better identify the mitochondrial changes induced by regorafenib that allow BCL-xL antagonism to synergistically induce cytotoxicity in hepatoma cells, we analyzed the protein levels of BCL-2 members with recognized importance in cell survival." (PMID 32024199, 2020). "The reduction in invasion, metastasis, and adhesion and the induction of apoptosis signals, including Bax, Bcl-2, and caspase-3, are related to the effect on hepatocellular carcinoma." (PMID 32410996, 2020). "A recent study indicates that OA can increase apoptosis via decreasing protein levels of B cell lymphoma-2 (Bcl-2) and increasing the levels of Bcl-2 associated X protein (Bax) and PARP in human hepatoma HepG2 cells." (PMID 33390956, 2020). "Opsin3 (OPN3), a member of the guanine nucleotide‐binding protein‐coupled receptor superfamily, has been identified to affect the apoptosis of hepatoma cells by modulating the phosphorylation of Akt and Bcl2/Bax." (PMID 31802643, 2020). "Polysaccharide from Lentinus edodes induced apoptosis in hepatocellular cancer cells by arresting cell cycle at G2/M phase, increasing ROS level and Bax expression, down-regulation of Bcl-2 expression and activation of caspase-3 expression." (PMID 33240031, 2020).
hepatocellular carcinoma (continued). "P-glycoprotein regulated drug efflux and Bcl-2 modulated drug resistance, both of which led to the failure of chemotherapy in hepatocellular carcinoma." (PMID 32579175, 2020). "Previous studies have shown that inhibition of Bcl‐2 expression can enhance the sensitivity of hepatoma cells to anti‐tumour drugs." (PMID 33090723, 2020). "Consistent with our findings it has been shown that Coronarin D triggers apoptosis by activating caspase–dependent proteins and altering the expression of Bcl–2, Bcl–xL, and Bak in human hepatoma cell lines." (PMID 31818017, 2019). "Modulation of the NF-κB/Bcl-2 signaling pathway has been shown by Western blot analysis to play a critical role in both of the invasion and proliferation of hepatocellular carcinoma (HCC) in a dose-dependent manner." (PMID 31781485, 2019). "DHA induces apoptosis through Bcl-2 down-regulation in human cervical cancer HeLa and Caski cells, and via Bim-dependent intrinsic pathway in human hepatocellular carcinoma HepG2 and Huh7 cells." (PMID 31719837, 2019). "Sorafenib-resistant hepatoma cells (HepG2R and Hep3BR) exhibited altered mRNA expression of BCL-2 and other anti-apoptotic family members, such as MCL-1, priming drug-resistant cancer cells to death by BH3-mimetics." (PMID 29682179, 2018). "SLC1A4 was found to be associated with human hepatocellular carcinoma, and CRYZ was proven to be involved in B-cell lymphoma 2 (BCL-2) overexpression in T-cell acute lymphocytic leukemia." (PMID 29344347, 2018). "Bcl-2 and Twist1 can be coactivated by hypoxia in hepatocellular carcinoma to promote tumor cell metastasis and vasculogenic mimicry, but their function in oral squamous cell carcinoma (OSCC) remains undefined." (PMID 28032603, 2017). "Other EP300-associated factor, PCAF, accelerates apoptosis by repressing a GLI/BCL2/BAX axis in hepatocellular carcinoma." (PMID 28341962, 2017). "It inhibited the proliferation and inducing apoptosis of human hepatocellular carcinoma cell line HepG2, and resisted the carcinoma by changing the Bcl-2 and nm23-H1 protein expression." (PMID 28099921, 2017). "Previous studies have suggested that the anti-apoptotic genes Bcl-2 and Bcl-xL were markedly upregulated in paclitaxel-resistant hepatoma cell line, and Bcl-xL expression was enhanced by paclitaxel treatment." (PMID 29216925, 2017). "Overexpression of DLC1 stimulates cell apoptosis by elevating caspase-3 activity and decreasing Bcl-2 level in hepatocellular carcinoma and cutaneous squamous cell carcinoma cells." (PMID 28903430, 2017). "Tubeimoside I, an ingredient derived from Bolbostemma paniculatum (Tu-Bei-Mu), up-regulates Bax/Bcl-2 and induces intrinsic apoptosis in hepatoma cells." (PMID 26828466, 2016). "In human and rat hepatocellular carcinoma cells, Ast has been shown to induce apoptosis while down-regulating anti-apoptotic Bcl-2 protein." (PMID 26978376, 2016). "TWIST1 is a transcription factor involved in EMT regulation, and it was reported that the Bcl-2/TWIST1 complex facilitates VM in hepatocellular carcinoma." (PMID 25895023, 2015). "Western blot analysis of PAPR, caspase-3, BAX, and Bcl2 also showed that CN30 induced apoptosis in hepatoma cells." (PMID 26393569, 2015). "LQ (400 μM) strongly reduced the expressions of Bcl-2 and Bcl-xL in hepatocellular carcinoma cells from 6 h to 24 h (P < 0.05)." (PMID 24738081, 2014). "In an experiment using mouse hepatoma and human hepatopblastoma cells, Nrf2 was shown to control cell apoptosis via upregulation of Bcl-2 transcription and downregulation of Bax." (PMID 24559268, 2014).
hepatocellular carcinoma (continued). "Our data demonstrate that embelin is able to change the mitochondrial membrane potential to promote the shift of Bax and Bcl-2 as well as the release of cytochrome c, which results in the apoptosis of HepG2 human hepatocellular carcinoma cells." (PMID 23170120, 2012). "In summary, our study demonstrated that embelin releases cytochrome c and activates the caspase family, resulting in the induction of hepatocellular carcinoma apoptosis by regulating the action of the Bcl-2/Bax family on the mitochondrial pathway." (PMID 23170120, 2012). "Our research found that after human hepatocellular carcinoma cells were treated with different doses of emblin for 48 h, Bax and Bcl-2 migrated, the mitochondrial membrane potential decreased, and cytochrome c was released." (PMID 23170120, 2012). "On the other hand, previous study has also indicated Bcl-2 protein expression in acute and chronic hepatitis, cirrhosis and hepatocellular carcinoma." (PMID 22216150, 2011). "Its effects on the apoptosis modulating proteins, such as Bcl-2, Bax, and Bid, had been demonstrated in Hep 3B hepatoma cells." (PMID 21423639, 2011). "High expression of Bcl-2 mRNA was observed in hepatoma cells that express the deletion forms of HBV large surface proteins." (PMID 22216150, 2011). "miR16-1 regulates the expression of bcl-2, which is important in retinoblastoma, and is located in a genomic region that is frequently lost in nasopharyngeal and hepatocellular carcinomas (HCCs)." (PMID 19865490, 2009). "TNF-α suppresses Bcl-2 in FaO rat hepatoma cells while it induces Bcl-2 in rat hippocampal neuron cells." (PMID 17570844, 2007). "We analyzed HO-1 cellular localization and the expression of HO-1, Bcl-2 and cell cycle related proteins under these conditions comparing them to hepatocellular carcinoma (HC)." (PMID 17169158, 2006). "Similarly, HT has been shown to inactivate AKT and NF-κB, leading to a reduced expression of Cyclin D1, c-Myc, and Bcl-2 in hepatocellular carcinoma models." (PMID 40725203, 2025). "According to a study on Cyclo(L-Leu-L-Pro) isolated from the sponge Callyspongia fistularis, the compound exhibited cytotoxic and apoptosis-inducing effects against human hepatocellular carcinoma HepG2 cells by significantly increasing the BAX/Bcl-2 protein expression ratio and activating caspase-3." (PMID 40867294, 2025). "After Bclaf1 overexpression was confirmed by Western blotting, the expression of Bcl-2, a key protein of mitochondrial apoptosis in hepatoma cells, was increased and that of Bax was decreased, and the Bcl-2/Bax ratio was increased compared with the findings in the blank control group (all p < 0.01)." (PMID 39444606, 2024). "In addition, the results of apoptosis-related proteins (Caspase-3, Cleaved Caspase-3, and Bcl-2) further revealed the mechanism of shFIGNL1-induced apoptosis of human hepatoma cells." (PMID 37929733, 2024). "The combination of curcumenol and 34 inhibited the proliferation, migration, and invasion of human hepatoma HepG2 cells, as shown by reduced levels of pSTAT3 and BCL-2, dose-dependently decreased hydrogen sulfide (H2S) synthetase, and downregulated VEGF and its downstream key genes pAkt and pERK1/2." (PMID 38535455, 2024). "↓ Bcl-2, ↑ caspase-3 expression in hepatocellular cancer cells (HepG2 and EAC)." (PMID 37762572, 2023).
hepatocellular carcinoma (continued). "(A16) extract-induced hepatoma cell apoptosis may depend on increased Bax and decreased Bcl-2 expression." (PMID 37189672, 2023). "Our results suggest that an important mechanism of curcumin inhibiting proliferation of hepatocellular carcinoma cells is to elicit apoptosis, which is in agreement with the downregulation of the anti-apoptotic protein Bcl-2 and the upregulation of the apoptotic proteins Bax and caspase-3." (PMID 37333486, 2023). "At the same time, CUR may decrease the expression of Bcl-2 protein, increase the release of cyt c, and promote the apoptosis of hepatoma cells." (PMID 36865794, 2023). "Through the decreased expression of PI3KR1, AKT1, and BCL2 mRNA levels compared with control group, we demonstrated that the inhibition of hepatocellular carcinoma by aloe-emodin could be mediated through the PI3K-AKT signaling pathway." (PMID 37900162, 2023). "During hepatocellular carcinoma induction, the expression of Bcl-2, a downstream target gene of p38MAPK, was decreased, disrupting the balance between Bax and Bcl-2, and leading to the relative overexpression of Bax, ultimately causing apoptosis in hepatocellular carcinoma cells." (PMID 35874633, 2022). "The pan-Bcl-2 inhibitor Obatoclax can sensitize hepatocellular carcinoma cells to promote the anti-tumor efficacy in combination with ICIs, for Obatoclax can sensitize T cell mediated killing by promoting T cell activation and the expression of effector cytokines in spleen and tumor." (PMID 35962453, 2022). "As2O3 could inhibit cell proliferation and promote cell apoptosis in hepatoma stem cell MHCC97H by down-regulating Bcl-2 expression." (PMID 35646647, 2022). "In addition, etoposide, but not staurosporine, bypasses the chemoresistance conferred by Bcl-2 in Hep3B hepatoma cells." (PMID 36555165, 2022). "Capsaicin is a natural vanilloid and may inhibit the growth of SK-Hep-1 hepatocellular carcinoma cells by inducing apoptosis via Bcl-2 downregulation and caspase-3 activation." (PMID 35388300, 2022). "The combination of Hydroxycamptothecin (0.625 μmol/L) and Celecoxib (30 mg/L) could promote cell apoptosis of human hepatoma cell line SMMC-7721 by down-regulating the expression of Bcl-2 and COX-2, up-regulating the expression of Bax." (PMID 35646647, 2022). "In addition, matrine-derived compounds can inhibit the development of hepatocellular carcinoma by reducing the expression of Bcl-2, inducing cell cycle arrest, reducing the number of EpCAM and CD133 cells, and inhibiting the expression of CSC markers." (PMID 36686745, 2022). "Therefore, KPL combined with ABT-199 had a mutual sensitization effect on the Bcl-2 proteins family in the endogenous mitochondrial pathway of apoptosis, thus inducing HepG2 hepatoma cells apoptosis." (PMID 36386146, 2022). "This was accomplished while boosting therapeutic potential in SMMC-7721 cells by modulating apoptotic pathways via increased production of Bax and caspase-3 and reduced levels of Bcl-2; thus, it can play an important role in the treatment of hepatocellular carcinoma." (PMID 36286449, 2022). "Encapsulating the anti-cell death gene si-BCL2 in hepatocellular carcinoma could finally effectively produce a synergistic tumor suppressor effect with PTX." (PMID 35745854, 2022). "Additionally*** ***, KAT2B is also capable of acetylating histone H4, inhibiting AKT signal as well as regulating GLI1/Bcl-2/Bax axis to induce apoptosis, thereby inhibiting occurrence and hepatocellular carcinoma development." (PMID 34130593, 2021).
hepatocellular carcinoma (continued). "Mitochondrial-localized PAK1 interacts with Bcl2 to allow hepatoma cells to become resistant to anoikis which might promote progression of HCC in patients with chronic HBV infection." (PMID 34456908, 2021). "Finally, our molecular docking results against EGFR and BCL2 molecular targets support the potency of L. sativum’s major compounds against hepatocellular carcinoma." (PMID 34579396, 2021). "NO induces apoptosis and inhibits autophagy in human hepatoma cells by disrupting the Beclin 1/VPS34 association and increasing the Bcl-2/Beclin 1 interaction, which may provide a novel strategy for the treatment of hepatocellular carcinoma (HCC)." (PMID 34768858, 2021). "Moreover, stigmasterol was formerly studied for activating apoptosis in hepatocellular carcinoma cell lines through upregulation of the Bax protein and downregulation of the Bcl-2 protein." (PMID 32069824, 2020). "In addition, the reduction of invasion, metastasis, and adhesion and the induction of apoptosis-related targets, including Bax, Bcl-2, and caspase-3, are related to its effect on hepatocellular carcinoma." (PMID 32410996, 2020). "In this study, we overexpressed Bcl‐2 in hepatoma cells and then treated those cells with ATRA." (PMID 33090723, 2020). "For example, coculture of MSCs with hepatoma cells results in an increase in tumor cell apoptosis and decrease in proliferation by down-regulating Bcl-2, c-Myc, proliferating cell nuclear antigen (PCNA), and survivin protein levels in hepatoma tumor cells; all of them are targets of Wnt signaling." (PMID 32793565, 2020). "Based on the findings to date, we hypothesized that LETM1 regulates autophagy and apoptosis through activation of AMPK-mediated Beclin-1/Bcl-2 complex dissociation in hepatocellular carcinoma." (PMID 33552978, 2020). "STC2 overexpression in hepatocellular carcinoma could lead to poor prognosis, which might be due to its induced increase of P-glycoprotein and Bcl-2 protein expression levels." (PMID 32579175, 2020). "Similarly, miR-34a was shown to repress BCL2 expression, leading to sensitisation to sorafenib-induced apoptosis in hepatocellular carcinoma and increased levels of apoptosis via the mitochondrial death cascade in non-small cell lung carcinoma (NSCLC) cells." (PMID 35582270, 2019). "In this way, to determine whether the pure compounds induce apoptotic cell death by regulating antiapoptotic (Bcl-2) and proapoptotic (Bax) proteins in the hepatocellular carcinoma Hep3B/PTX cells, expression of Bax and Bcl-2 was analyzed by RT-PCR." (PMID 31590262, 2019). "Specifically, RAB31 might promote hepatocellular carcinoma progression by inhibiting cell apoptosis induced by the PI3K/AKT/Bcl‐2/BAX pathway." (PMID 29957874, 2018). "Furthermore, mRNA level of anti-apoptosis related gene Bcl-2 was observed to elevate in hrIL-23 treated hepatoma cells." (PMID 29983862, 2018). "Moreover, HJT exerted antitumor effect through increasing the expression of Bax and Bak and decreasing the expression of Bcl-2 and Bcl-xL via inhibition of the NF-κB activity, and consequently inducing the mitochondria-dependent apoptosis in hepatoma cells." (PMID 28702078, 2017). "In order to determine whether the pure compounds induce cell death by apoptosis by regulating anti-apoptotic (Bcl-2) and pro-apoptotic (Bax) proteins in the hepatocellular carcinoma Hep3B cells, expression of Bax and Bcl-2 was analyzed by RT-PCR." (PMID 28441723, 2017). "However, despite relatively low Bcl-2 expression, hepatocellular carcinoma cell lines SNU423 and HuH7 were both intrinsically resistant to LCL161." (PMID 28424988, 2017).